ATG12 (autophagy related 12)
Diseases named in the same sentence as ATG12 in open-access papers (continued):
Sharing a sentence is not in itself a finding about the gene and the disease.
pancreatic cancer (10 papers, 2014 to 2021). "Previous study reported that ATG12 was associated with radioresistance of pancreatic cancer cells." (PMID 29459645, 2018). "Furthermore, an association between decreased ATG12 expression and elevated miR-23b levels was observed in human pancreatic cancer tissue, indicating that miR-23b might affect autophagy activity in pancreatic cancer cells." (PMID 33317198, 2020). "For instance, miR 23b regulates radioresistance of pancreatic cancer cells by targeting autophagy-related 12 (ATG12)." (PMID 33402116, 2021). "We also investigated the correlation between the expression of NURR1 and ATGs (ATG7 and ATG12) in pancreatic tumor samples by performing correlation analysis." (PMID 35582016, 2021). "Wang's laboratory reported that reduced miRNA MIR23B increases ATG12 and autophagy to promote radioresistance in pancreatic cancer cells." (PMID 25053988, 2014). "This analyses also demonstrated a significant increase in the expression level of ATG12 in pancreatic tumors, (T = 179) compared with normal tissue samples (N = 171) and Kaplan–Meier analysis shows that high expression of ATG12 corresponds to poor patient survival rate." (PMID 35582016, 2021). "Here, we knocked out ATG12 in a pancreatic cancer cells and acinar cells using CRISPR/Cas9." (PMID 29888283, 2018). "To study the prognostic significance of ATG7 and ATG12 in PDA, we examined TCGA, which showed a significant increase in expression of ATG7 in pancreatic tumors (T = 179) compared with normal tissue samples (n = 171)." (PMID 35582016, 2021). "In the present study, we also found that down‐regulating ATG12 by reducing the expression of PTBP3 inhibited autophagy and increased sensitivity to gemcitabine in pancreatic cancer cells." (PMID 31989778, 2020). "Moreover, NURR1 regulated expression of two major autophagic genes, ATG7 and ATG12, which are also overexpressed in pancreatic tumors and like NURR1 are negative prognostic factors for patient survival." (PMID 35582016, 2021).
ovarian carcinoma (8 papers, 2012 to 2022). A malignant neoplasm originating from the surface ovarian epithelium. "For example, Nrf2 induction by cisplatin is linked to the increased expression of autophagy-related genes, including Atg3, Beclin1 and Atg12, which contributes to the resistance against cisplatin treatment in ovarian cancer cells." (PMID 28341848, 2017). "Up-regulation of miR-30d contributes to ovarian cancer development by suppressing Beclin1, BNIP3L, ATG12, ATG5, ATG2 directly and inhibiting LC3-I conversion to LC3-II." (PMID 27825125, 2016). "In ovarian cancer, the oncomiR miR-30d was illustrated to impair autophagy by suppressing a multitude of autophagy-related genes including Beclin1, BNIP3L, ATG12, ATG5, ATG2 directly and inhibiting LC3-I conversion to LC3-II." (PMID 27825125, 2016). "Dasatinib and dihydroptychantol 2 were showed to inhibit ovarian cancer cells (SKOV3 and Hey) growth by inducing the expression of LC3B-II, Beclin1 and Atg12." (PMID 27825125, 2016). "Similar to our Grp78 data, silencing GADD 153 in ovarian cancer cells blocked DIM induced up regulation of LC3B, p62 and Atg12." (PMID 22564965, 2012). "Induction of AMPK, ATG12, beclin-1 and/or cleavage of LC3 occurred at physiologically attainable L-ASP concentrations (0.3–1 U/ml) in two ovarian cancer cell lines and the primary culture HMVEC cells; similar beclin induction results were observed in CAOV3 cells as well." (PMID 22333033, 2012). "Pharmacologically inhibiting ER stress using chemical inhibitors such as cycloheximide or mithramycin not only blocked the induction of Grp78, IRE1 or GADD 153, but also inhibited DIM induced expression of Atg12, LC3B and p62 in SKOV-3 and OVCAR-3 ovarian cancer cells." (PMID 22564965, 2012).
cervical carcinoma (7 papers, 2015 to 2025). A carcinoma arising from either the exocervical squamous epithelium or the endocervical glandular epithelium. "Yet, miR-378 was found to play a potential role in the metastatic stage via targeting the autophagy related-12 (Atg12) in cervical cancer cells." (PMID 39227808, 2024). "Our study demonstrates that gene silencing of Atg12 and Beclin1, or cotreatment of the cervical cancer with 3-MA or BA, inhibits LicA-induced autophagy." (PMID 26311737, 2015). "A pioneering study demonstrated that AS-IV could suppress the progression of cervical cancer by activating the Atg7/Atg12/LC3 autophagy axis through targeting DCP1A and TMSB4X." (PMID 41155562, 2025). "RAME treatment increased the mRNA levels of ATG genes (ULK1, ATG5, BECN1, ATG7, ATG12, and ATG13) dose dependently in cervical cancer cells." (PMID 31387554, 2019). "No direct prognostic value of ATG12 was observed in the TCGA cohorts cervical cancer, bladder cancer, glioblastoma, esophageal cancer, liver cancer and lung cancer." (PMID 34904929, 2022). "Furthermore, they found that in cervical cancer tissues with lymph node metastasis, miR-378 was upregulated and ATG12 was downregulated when compared with lymph node negative cases." (PMID 35456001, 2022).
glioma (7 papers, 2019 to 2021). A benign or malignant brain and spinal cord tumor that arises from glial cells (astrocytes, oligodendrocytes, ependymal cells). "We also further evaluated a range of autophagy-related proteins, including mTOR, p-mTOR, ATG5, ATG12 and Beclin-1 in glioma cells." (PMID 34683892, 2021). "The inhibition of autophagy by shRNA targeting ATG12 in a glioma 3D organotypic model has been shown to impair cell invasion but does not affect cell viability, proliferation and cell migration." (PMID 33743781, 2021). "For instance, miR-454-3p was documented to target ATG12 to repress glioma cell proliferation and invasion." (PMID 33363140, 2020). "However, the expression of mTOR, p-mTOR, ATG5, ATG12 and Beclin-1 in glioma cells was not increased after Co3O4 NPs treatment, which confirmed that Co3O4 NPs did not induce autophagy." (PMID 34683892, 2021).
lung adenocarcinoma (7 papers, 2017 to 2022). A carcinoma that arises from the lung and is characterized by the presence of malignant glandular epithelial cells. "The expression of miR-200b was inversely correlated with autophagy-associated gene 12 (ATG12) in docetaxel-resistant lung adenocarcinoma cells." (PMID 35682560, 2022). "The downregulation of ATG12 by miR-200b enhanced the chemosensitivity of lung adenocarcinoma cells to docetaxel." (PMID 35682560, 2022). "We found that ATG10 rs10036653, ATG12 rs26538, ATG16L1 rs2241880 and ATG16L2 rs11235604 were significantly associated with survival of lung adenocarcinoma patients (all P < 0.05)." (PMID 29259263, 2017). "ATG10 rs10036653, ATG12 rs26538, ATG16L1 rs2241880 and ATG16L2 rs11235604 were significantly associated with OS of gefitinib-treated advanced lung adenocarcinoma patients (all P < 0.05)." (PMID 29259263, 2017). "Similarly, an mRNA expression database (containing 440 lung adenocarcinoma cases) for pro-autophagy markers was queried and the results showed that high expression of BECN1, ATG12, and DRAM1 are closely linked to increased survival among lung adenocarcinoma patients." (PMID 31101821, 2019). "In lung adenocarcinoma, lncRNA KCNQ1OT1 was also reported to upregulated radioresistance via miR-372-3p/ATG5 and ATG12 axis." (PMID 35600868, 2022).
diabetes (6 papers, 2018 to 2025). "The critical steps of Atg8 and Atg12 conjugation are directly involved in ATG7 which plays a role in the development of a transgenic animal model of diabetes." (PMID 33691614, 2021). "Results showed that expression of Atg12 was significantly decreased in STZ-diabetic (STZ-NC) mice compared to control mice injected with NC oligonucleotides (Control-NC) just 2-weeks post diabetes induction." (PMID 29725042, 2018). "At 16 weeks post diabetes, Atg12 expression was again significantly decreased, as also LC3 in STZ-NC mice compared to Control-NC mice and this effect was significantly reversed in kidneys of STZ-LNA mice." (PMID 29725042, 2018). "Elevated p62 levels, decreased ULK1 and autophagy-related 12 (Atg12), as well as a reduced LC3B/LC3A ratio in their kidneys, are consistent with diabetes-induced autophagy suppression." (PMID 39201721, 2024). "Another cellular process affected by GABA tea in STZ-induced diabetes is autophagy as seen by decreases in related protein levels including Beclin 1, ATG7, ATG12, LC3-I, and LC3-II following treatment with GABA tea." (PMID 33041786, 2020). "At both time-points, the kidneys of vehicle-injected diabetic mice had higher ratio of p-mTOR to mTOR, increased abundance of p62, lower abundance of ULK1 and Atg12, and reduced ratio of LC3B to LC3A compared to non-diabetic animals, consistent with diabetes-associated suppression of autophagy." (PMID 38443965, 2024). "As a key to illuminate the crucial role of autophagy in diabetes progression, immunoblotting analysis unraveled the altered expression of some autophagic signals including light chain IIIB (LCIIIB), Beclin I, ATG12, and p62 proteins in non-obese diabetic (NOD) mice." (PMID 33041786, 2020).
head and neck squamous cell carcinoma (6 papers, 2014 to 2024). A squamous cell carcinoma that arises from any of the following anatomic sites: lip and oral cavity, nasal cavity, paranasal sinuses, pharynx, larynx, and salivary glands. "It was reported that the C/C genotype of rs26537 in ATG12 upregulated ATG12 mRNA levels in head and neck squamous cell carcinoma in Chinese Han populations." (PMID 37629426, 2023). "In head and neck squamous cell carcinoma (HNSC), study showed that high expression level of ATG12 significantly increased the death risk after adjusting for age, gender, clinical stage, smoking and drinking status." (PMID 33837652, 2021). "MiR-630 was also found to be upregulated in head and neck squamous cell carcinoma after cisplatin treatment and can modulate the protein expression of ATG5, ATG6/BECN1, ATG10, ATG12, ATG16L1 and UVRAG." (PMID 24621930, 2014). "In this study, we determined autophagy-defects in head and neck squamous cell carcinoma (HNSCC) and observed that expression of ATG12 (autophagy related 12) was lost in 25%-40% of HNSCC." (PMID 34904929, 2022). "One study showed that autophagy-defective head and neck squamous cell carcinoma (HNSCC) cells lacking ATG12 have reduced hypoxia tolerance, and are sensitive to anti-cancer therapies." (PMID 38778409, 2024).
prostate carcinoma (6 papers, 2014 to 2024). A carcinoma that arises from epithelial cells of the prostate gland. "In addition, mutation at an ATG5 splice site has been reported in a prostate cancer cell line, which prevents ATG12 conjugation and leads to the degradation of ATG12 and ATG16L1, thus inhibiting autophagy." (PMID 34829881, 2021).
viral infection (6 papers, 2012 to 2024). "To test the role of autophagy in virus infection, we used short hairpin RNAs (shRNAs) to silence autophagy genes, ATG12, ATG14, or Beclin1, in iSLK.219 cells." (PMID 31375594, 2019). "Increased expression was also observed for the cell-surface phagocytosis receptor, Fcgr3a, and genes linked to autophagy (Atg12, Snx4), antigen presentation pathway (RT1-CE6), Itm2a, involved in immunoglobulin production, and Oas1g, an immune response protein against viral infection." (PMID 34587117, 2021). "However, key autophagy genes including ATG1, ATG3, ATG9, ATG12, and ATG16L1 were significantly upregulated in horses after viral infection." (PMID 39287214, 2024).
liver cancer (5 papers, 2022 to 2023). An epithelial or non-epithelial malignant neoplasm that arises from the liver. "Studies have revealed that endoplasmic reticulum stress can inhibit the expression of autophagy‐related genes, including ATG12 and ATG5, allowing liver cancer cells to evade autophagic degradation and enhance their capacity for growth and proliferation." (PMID 37728036, 2023). "SMAD2 and SMAD3 correlated with autophagy-related scores (based on ATG12, ATG7, ATG3, ATG5, ATG4B, PIK3C3, PRKAA2, and GABARAPL1) in liver cancer." (PMID 37790613, 2023). "Statistical analysis indicated that SH3BGRL is correlated to ATG5 expression level, but not ATG12 level in liver cancers." (PMID 37138798, 2023).
chondrosarcoma (4 papers, 2017 to 2020). A malignant cartilaginous matrix-producing mesenchymal neoplasm arising from the bone and soft tissue. "HOTAIR sponged miR-454-3p and indirectly upregulated ATG12 to promote cancer progression in chondrosarcoma cells." (PMID 33050642, 2020). "HOTAIR knockdown impeded chondrosarcoma progression in vitro and in vivo through inhibiting autophagosome formation by downregulating ATG12." (PMID 33050642, 2020). "In chondrosarcoma, increasing hsa-miR-454-3p can downregulate Stat3 and Atg12 to inhibit chondrosarcoma growth." (PMID 29744354, 2018). "For the first time, we report that miR-454-3p functions as an anti-oncogene in chondrosarcoma cells by targeting Stat3 and Atg12." (PMID 28182000, 2017). "Taken together, this study reveals for the first time that miR-454-3p increases after HOTAIR knockdown to inhibit chondrosarcoma cell growth by targeting Stat3 and Atg12." (PMID 28182000, 2017).
osteosarcoma (4 papers, 2018 to 2024). A usually aggressive malignant bone-forming mesenchymal neoplasm, predominantly affecting adolescents and young adults. "A previous study revealed that demethylation-activated miR-570-3p suppresses LCMR1 and ATG12, contributing to the anti-metastatic effects of metformin in human osteosarcoma." (PMID 38890707, 2024). "Our results, for the first time, presents evidence that the miR-570-3p-mediated suppression of LCMR1 and ATG12 is involved in the metformin-induced inhibition of metastasis in osteosarcoma cells." (PMID 29795113, 2018). "In addition, we examined the effects of metformin on the expression of LCMR1 and ATG12 in osteosarcoma cells." (PMID 29795113, 2018). "Our western blot assay suggested that LCMR1 and ATG12 expression was notably increased in metastatic osteosarcoma compared with the primary non-metastatic ones." (PMID 29795113, 2018). "Additionally, we analyzed the expression of LCMR1 and ATG12 in metastatic and primary non-metastatic osteosarcoma tissues." (PMID 29795113, 2018).
thyroid cancer (4 papers, 2022 to 2024). "To explore the role of ubiquitin-like proteins (ISG15, ATG8, FAT10, NEDD8, SUMO1, UFM1, URM1 and ATG12) in thyroid cancer, we integrated the datasets (GSE33630, GSE29265 and GSE76039) and analyzed 65 NT, 69 PTC and 40 ATC samples." (PMID 37501099, 2023). "Five hundred and sixty-seven miRNAs associated with nine autophagy proteins (ULK1, ATG16L1, MAP1LC3B, PRKAA1, ATG12, ATG 14, ATG5, mTOR and BECN1) were identified, of which sixty-two are accompanied by thyroid cancer, and only miR-125b is associated with the autophagy modulation in this pathology." (PMID 36980957, 2023).
bladder cancer (3 papers, 2017 to 2024). "We next determined whether the concurrent inhibition of autophagy activities by specific suppression of ATG12, one of the key transcription factors for LC3 expression, could also enhance the anti-cancer effects of EGFR inhibitors in human bladder cancer cells." (PMID 28165387, 2017).
colon cancer (3 papers, 2019 to 2025). "The knockout of autophagy-related genes RB1CC1, ATG9A, and ATG12 significantly increased tumor cell susceptibility to T-cell killing in breast and colon cancers and enhanced the anti-cancer effect of PD-1 and CTLA-4 checkpoint inhibitors." (PMID 40641524, 2025). "In breast and colon cancers, the sensitivity of tumor cells to T-cell killing was significantly enhanced by knocking out autophagy-related genes RB1CC1 (RB1 inducible coiled-coil 1), ATG9A, and ATG12." (PMID 40641524, 2025).
lung carcinoma (3 papers, 2017 to 2022). "However, the alteration of the other autophagy-regulating proteins (Atg5, Atg12, and Beclin-1) was not significantly detected in human lung cancer cells cultured with 50 μM cisplatin compared to those non-treated control cells." (PMID 34321115, 2021).
Parkinson disease (3 papers, 2020 to 2024). A progressive degenerative disorder of the central nervous system characterized by loss of dopamine producing neurons in the substantia nigra and the presence of Lewy bodies in the substantia nigra and locus coeruleus. "Sequence variants affecting the expression levels of ATG12 (115842507G>T, 115842394C>T and 115841817_18del) and ATG7 (11313449G>A, 11313811T>C, 1313913G>A and 11314041G>A) are present in patients with sporadic Parkinson’s disease." (PMID 33147747, 2020). "BSJDF was found to improve cell survival in an MPP+-induced cell model of Parkinson’s Disease by inducing autophagy, as evidenced by increased protein expression of Atg12 and LC3, and upregulated Atg12 mRNA expression." (PMID 38256144, 2024). "In the substantia nigra of a Parkinson’s disease (PD) rat model, p62, Atg5, Atg12, LC3, and Atg16l1 were expressed, while Atg10 was not expressed." (PMID 36598250, 2023).
renal clear cell carcinoma (3 papers, 2020 to 2022). "Following a different approach, a novel, short ATG12 variant has been recently found in clear cell renal cell carcinoma." (PMID 35158828, 2022). "The short ATG12 variant is formed at the expense of the canonical isoform and, as it lacks the functionality of the latter in autophagy, this may be one of the causes by which inactivating mutations of SETD2 are associated with the development of clear cell renal cell carcinoma." (PMID 35158828, 2022).
Ataxia (2 papers, 2016 to 2023). Ataxia refers to impaired coordination of voluntary muscle movement. "In summary, we demonstrate that the homozygous E122D mutation of ATG5, a unique mutation found in two human subjects with ataxia, results in reduced conjugation to ATG12 and in an overall decrease in autophagy activity." (PMID 26812546, 2016). "Autophagy-related 12 (ATG12, MIM*609608) is a gene involved in cellular autophagy, and homozygous missense variants in this gene have been related to ataxia, developmental disorder, and mental retardation." (PMID 37510409, 2023).
breast tumor (2 papers, 2018 to 2021). "Immunohistochemistry (IHC) data showed that ATG12 protein is expressed in human breast tumor tissues." (PMID 33801244, 2021). "We further showed that ATG12 expression in breast tumors containing ERBB2 correlated with a worse patient survival outcome." (PMID 33801244, 2021). "Similar observations have been made in other breast tumor models by showing that CQ but not knockdown of Beclin 1 or ATG12 sensitized the tumor to chemotherapy." (PMID 29774126, 2018).
colitis (2 papers, 2020 to 2024). Inflammation of the colon. "The autophagy-related (Atg) genes control autophagosome formation through the Atg12-Atg5 and LC3-II (Atg8-II) complexes, and recent studies have noted that knockout of Atg genes in mice caused aggravation of colitis." (PMID 32013062, 2020). "To further explore the impact of the Xianhecao-Huanglian drug combination on autophagy in DSS-induced IBD mice, we examined the expression of proteins associated with autophagy, including ATG12, Beclin-1, LC3A/B, and p62, in colitis tissues using Western blot analysis." (PMID 39187810, 2024).
colorectal tumors (2 papers, 2018 to 2022). "In contrast, different research discovered frameshift mutations with single nucleotide repeats in ATG12 genes in gastric and colorectal tumors, which may contribute to the advancement of cancer by dysregulating the autophagy process." (PMID 36544483, 2022).